HLA-G (major histocompatibility complex, class I, G)
Diseases named in the same sentence as HLA-G in open-access papers (continued):
Sharing a sentence is not in itself a finding about the gene and the disease.
tumor (continued). "Unfortunately, no relation between concomitant tumour HLA-G expression and HLA-class I downregulation and clinical outcome of patients was investigated in this study." (PMID 34361031, 2021). "Studies showing simultaneous expression of tumour HLA-class I and HLA-G molecules did not reveal significantly poor clinical patient outcome." (PMID 34361031, 2021). "The anti-HLA-G scFv may compete with LILRB1 and KIR2D4 receptors on NK cells for HLA-G protein on the tumor membrane, thereby activating NK cell cytotoxicity by downregulating phosphorylated SHP-1 and upregulating phosphorylated Syk/Zap70." (PMID 34663641, 2021). "Despite the difference in when a tumour sample was considered HLA-G-positive, the percentages of HLA-G-positive tumour samples did not vary as much as one would expect between these studies." (PMID 34361031, 2021). "In preclinical murine models, HLA-G could promote tumor immune escape and growth through murine MDSC proliferation and Th2 cytokine production, or reduce T and B cell tumor infiltrate, impair B cell immune responses in immunocompetent mice." (PMID 33329527, 2020). "Thus, HLA-G:ILT2 is a potent immune checkpoint and constitutes a potential new target in anti-tumor therapies." (PMID 33505397, 2020). "Some tumor regions exhibited strong immunostaining with anti-VEGF-A whereas no label was found for HLA-G or ILT4." (PMID 32620162, 2020). "The possibility that an intricate interplay between angiogenesis and immune-checkpoints might exist lead us to evaluate tumor angiogenesis, by means of VEGF expression together with the immune checkpoint HLA-G/ILT4." (PMID 32620162, 2020). "Due to these limitations, experiments related to HLA-G expression and functions on tumor cells are not trivial." (PMID 32922387, 2020). "Several studies have demonstrated that when HLA-G or a nonclassical MHC I are highly expressed on the surface of tumor cells, the killing effect of T cells and NK cells can be inhibited." (PMID 31980023, 2020). "Surprisingly, there is a discrepancy between the frequent expression of HLA-G in tumor lesions and the lack of HLA-G expression in most cancer cell lines." (PMID 32560316, 2020). "This subpopulation of patients was excluded—as HLA-G and -F are mainly expressed in tumour, but not in stromal tissue—in order to maximize the tumour tissue content within the lysate." (PMID 32978482, 2020). "Demethylation is a common mechanism exploited by cancer cells to induce gene transcription and can explain the difference between HLA-G expression in vivo and in vitro when there is no selection pressure from the tumor microenvironment." (PMID 32560316, 2020). "Furthermore, interaction between HLA-G and the ILT4 receptor on CRC and NSCLC cells resulted in the proliferation, migration and invasion of these cells, thereby promoting tumor progression." (PMID 33213057, 2020). "The expression of the nonclassical HLA-G molecules in laryngeal lesions was reported as biomarkers of tumor invasiveness." (PMID 31739287, 2019). "For example, tumor cells often upregulate the expression of KIR ligands, such as HLA-G." (PMID 31847387, 2019). "HLA-G is a non-classical MHC-I molecule expressed in several tumor types including melanoma, glioblastoma, colorectal, ovarian and cervical tumors." (PMID 31540045, 2019). "While HLA-Gpos suppressor T cells were not increased in the peripheral blood of EwS patients, HLA-G was locally expressed on the tumor cells and/or on infiltrating lymphocytes in 16 of 47 pretherapeutic tumor biopsies and in 4 of 12 relapse tumors." (PMID 29464090, 2018). "We conclude that in our patient cohort HLA-G expression in the tumor microenvironment occurs independent of clinical parameters of the disease and response to standard cytotoxic agents." (PMID 29464090, 2018).
tumor (continued). "HLA-G is a crucial MHC-I molecule and plays an essential role in maintaining immune tolerance and inhibiting the functions of immunocompetent cells to support tumor cells escape from immunosurveillance." (PMID 30061885, 2018). "HLA-G interaction with ILT2 and CD94/NKG2A results in the inhibition of NK-cell cytotoxicity, IFN-γ secretion, and chemotaxis, while sMICA–NKG2D binding impairs NK-cell tumor-specific cytotoxicity, NKG2D expression, and homeostatic maintenance." (PMID 28377768, 2017). "The lack of labeling of tumor sections with this antibody normally accounts for the absence of HLA‐G expression." (PMID 28815885, 2017). "HLA-G transcriptional activity in HLA-G− tumor cells was not followed by a concomitant/simultaneous protein detection." (PMID 28781970, 2017). "We demonstrated that HLA-G was not expressed in the tumor cells of HL patients with +3027-C/A genotype and present only in a minority of cases (20%) with the wild type +3027-C/C genotype." (PMID 29285306, 2017). "Classic human leukocyte antigen-I (HLA-Ia) molecules are reduced or absent on the surface of tumor cells, whereas non-classic HLA (HLA-Ib) molecules, such as HLA-G and HLA-E, are highly expressed on the surface of tumor cells." (PMID 27322426, 2016). "It is well established that tumor cells, cytotrophoblast cells, and MSCs secret HLA-G-bearing EVs in addition to non-vesicular soluble HLA-G." (PMID 27199995, 2016). "Without any doubt, the neo-ectopic expression of HLA-G molecules either on the surface of tumor cells or released as soluble forms can be considered a critical factor for cancer progression." (PMID 27199995, 2016). "The metastatic tumor cells showed less expression of HLA-E (26 %) and HLA-G (28 %), however, this was not significant." (PMID 27895918, 2016). "HLA-G is a non-classical HLA class I molecule whose aberrant expression in a wide variety of cancers has been suggested as a mechanism by which tumour cells can escape immunosurveillance." (PMID 27517300, 2016). "Experiments performed in the context of the present study confirmed that the life time of acquired HLA-G at the surface of acceptor tumor cells is limited, and of the order of 24 h (data not shown)." (PMID 25887663, 2015). "This does not involve blocking HLA-G to favor antitumoral response against solid tumor but, conversely, using the antiproliferative properties of HLA-G to limit tumor progression for hematological malignancies." (PMID 24800261, 2014). "Sections of this TMA were immunohistochemically stained and quantified for presence of Foxp3+ cells (Tregs) and tumor expression of HLA Class I and non-classical HLA-E and HLA-G." (PMID 24997850, 2014). "For HLA-G, 31 patients (6.4%) had absence of tumor staining, 319 patients (65.9%) had a weak tumor staining, 103 patients (21.3%) had a moderate tumor staining and 31 patients (6.4%) had a strong tumor staining." (PMID 24997850, 2014). "HLA-G is expressed on HRS cells in more than 50% of HL patients and is associated with lack of HLA class I expression and tumour cell EBV status." (PMID 24959336, 2014). "Evidence for epigenetic control of HLA-G is initially reported for seven different HLA-G negative tumor cell lines." (PMID 25143957, 2014). "In univariate analysis, advanced stage disease (HR 4.7; 95% CI: 1.16–19.17), IDS (HR 1.8; 95% CI: 1.15–2.91), macroscopic residual tumour (HR 2.6; 95% CI: 1.57–4.43), and lack of expression of HLA-G (HR 1.69; 95% CI: 1.14–2.51) were related to worse survival." (PMID 24987709, 2014). "By contrast, no tumor development is observed when HLA-G is blocked by a specific antibody, demonstrating the specificity of the effect." (PMID 24839609, 2014). "These include intrinsic defects of tumor cells such impaired expression of the HLA class I related antigen processing machinery and functional alterations of the tumor microenvironment (TM) induced by NB cell-derived immunosuppressive molecules as MICA and HLA-G." (PMID 23805414, 2013).
tumor (continued). "Whether the absence of HLA-G and tumour-infiltrating lymphocytes predicts response to pembrolizumab remains under investigation." (PMID 41567618, 2026). "Additionally, while tumor cells contain immune suppressive molecules such as TGF-beta, soluble HLA-G, and IL-10, intra alia, senescent cell lysates contain molecules that may actually stimulate immunity through dendritic cell maturation such as interleukin-6." (PMID 41316207, 2025). "NANPs designed to deliver siRNAs against cancer immunity-inhibitory machinery – e.g., PD-1 and CTLA4 on T-cells, PD-L1 on cancer cells and APCs, VEGF on tumor vasculature, LAG, TIM3, HLA-G, TGFβ on tumor cells – may aid in overcoming barriers created by four steps of the cancer immunity cycle: III." (PMID 40831543, 2025). "In addition, tumour cells can increase the expression of non-classical HLA class I molecules, such as HLA-E and HLA-G." (PMID 40639721, 2025). "Hyperactive metabolism and disproportionate blood supplies render the tumor microenvironment hypoxic, leading to the accumulation of vascular endothelial growth factor (VEGF), which fosters angiogenesis and concomitantly arouses the upregulation of multiple immune checkpoints, including HLA-G." (PMID 38310272, 2024). "This overexpression is influenced by epigenetic mechanisms (DNA methylation and histone modifications), and tumor microenvironmental factors, particularly hypoxia, which stabilizes the hypoxia‐inducible factor 1 (HIF‐1α) and other factors, leading to increased HLA‐G expression." (PMID 38882209, 2024). "This is in line with our observations, that immune cells in the TIME of HLA-G high MIBC – especially of evasion phenotype MIBCs- exhibited an upregulation of crucial immune checkpoint proteins like TIGIT, PD-L1, LAG3, and CTLA-4 on tumor cells (PD-L1) and immune cells (all proteins)." (PMID 39469714, 2024). "JNJ-78306358 simultaneously binds to the α3 domain of HLA-G isoforms on tumor cells and to the CD3 receptor complex on T cells, mediating immune synapse formation and tumor cell killing by cytotoxic T cells, while mitigating the immunosuppressive tumor microenvironment." (PMID 39105878, 2024). "Moreover, to identify the efficacy of Nb‐TriTE that dual‐targeting PD‐L1 and HLA‐G for the treatment of NSCLC tumors with variations in PD‐L1 and HLA‐G expression, a tumor heterogeneity PBMC‐CDX‐NSG murine model was conducted by inoculating ovPD‐L1/ovHLA‐G A549 cells into mice." (PMID 39234811, 2024). "For instance, in cancers marked by the overexpression of non-classical HLAs, like HLA-G or HLA-E, interventions aimed at blocking their interactions with immune receptors could potentially restore immune surveillance and amplify anti-tumor responses." (PMID 39766165, 2024). "In conclusion, we have developed a dual‐targeting mRNA‐engineered Nb‐CAR.BiTE‐Vδ2 γδT therapy is capable of overcoming the HLA‐G/PD‐L1 checkpoint dilemma and even destroying antigen‐inadequate tumor cells, which leads to potent anti‐tumor activity with no apparent toxicity." (PMID 37078788, 2023). "In addition, soluble HLA-G released by tumour cells is unlikely to act as a decoy and significantly block anti-HLA-G CAR-T cells’ functions." (PMID 36053326, 2023). "The HLA-G molecule can interact with leukocyte receptors (e.g., ILT-2 [LILRB1/CD85j], ILT-4 [LILRB2/CD85d], and KIR2DL4 [CD158d]), mostly on CD8+ T and natural killer (NK) cells, inducing inhibitory cytotoxic responses, facilitating tumor cell proliferation and spread." (PMID 37569841, 2023). "Despite the direct interaction between immune receptors and tumor cells expressing HLA-G, this may not be adequate to account for the evasion of malignant cells from the immune system." (PMID 37048814, 2023). "Indeed, the up-regulation of TIM-3 and CTLA-4 on T lymphocytes driven by HLA-G may be dampened by the inhibition of HLA-G/ILT2 interaction, thus increasing the re-activation of T cell responses against tumor cells." (PMID 35328349, 2022).
tumor (continued). "Our study indicates that the expression and presentation of molecules like HLA‐G, which promote the formation of high‐affinity NKG2A ligands could not only represent an immune evasion strategy for tumours, but also a potential resistance mechanism in therapies with ICIs targeting NKG2A." (PMID 35596615, 2022). "Our results indicate that peptides displayed by HLA‐E molecules on tumour cells might influence the effectivity of NKG2A‐ICI therapy and potentially suggest novel approaches for patient stratification, for example, based on tumoral HLA‐G levels." (PMID 35596615, 2022). "Thus, novel immunotherapeutic strategies aimed at blocking the interaction of PD-1 and CTLA-4 with their ligands, paralleled by the targeting of HLA-G/ILT2 interaction, may greatly enhance the rescue of anti-tumor immune response." (PMID 35328349, 2022). "Specific tumour cell surface proteins (e.g. HLA-G, PD-L1, CDX2) either alone or in combination with the relative presence of immune cells (CD3 and CD8 positive T-cells) in the tumour tissue may describe the cancer cells’ ability to escape eradication by the immune system." (PMID 35027037, 2022). "Thus, in subjects affected by VSCC, HLA-G, and IDO, immune-suppressive functions are correlated, and the two molecules may co-operate in the inhibition of anti-tumor immune response, worsening the clinical outcome of patients." (PMID 35328349, 2022). "The anti-HLA-G scFv component may compete with LILRB1 and KIR2D4, both of which are expressed by NK cells, to hijack tumor HLA-G and activate NK cell cytotoxicity by downregulating phosphor-SHP-1 and upregulating phosphor-Syk/Zap70 (thereby converting inhibitory signals to activating signals)." (PMID 34663641, 2021). "In addition to immune suppressive functions, HLA-G/ILTs can promote intratumor vascular remodeling by enhancing vascular endothelial growth factor-C (VEGF-C) expression, and increase tumor metastasis by inducing cancer promoting factor matrix metalloproteinases (MMPs) expression." (PMID 34276691, 2021). "Additionally, hypoxia induces HLA-G transcription and protein production in a series of HLA-G-negative tumor lineages." (PMID 34884849, 2021). "In addition, hypoxia can change HLA-G expression in trophoblast cells and tumor cells whereas there is no reduction of HLA-G expression in cytotrophoblasts by short-term exposure to hypoxia." (PMID 32997116, 2021). "Moreover, HLA-G-dressed NK cells suppress the cytotoxic function of other NK cells expressing ILT2, the inhibitory receptor for HLA-G, which possibly leads to the immune escape of HLA-G-expressing tumor cells." (PMID 34069602, 2021). "Therefore, more upstream indications of presence of HLA-G in tumour lesions (e.g., through mRNA expression) is not a fair reflection of the actual expression of HLA-G on protein level." (PMID 34361031, 2021). "A recent study that tumor cells may upregulate non-classical HLA molecules, such as HLA-G, which can be modulated by cytokines like IL-10 and IFN-γ to evade immunosurveillance." (PMID 32083005, 2020). "Similarly, some tumor regions exhibited strong immunostaining with anti-HLA-G or anti-ILT4 whereas no label was found for VEGF-A." (PMID 32620162, 2020). "Hence, HLA-G can also initiate not immune-related tumor-promoting processes in neighboring tumor cells." (PMID 33213057, 2020). "It has to be mentioned that that HLA-G isoform expression is not homogeneous within carcinoma entities and mRNA as well as protein expression or synthesis may vary within one tumor." (PMID 31013867, 2019). "Importantly, the sHLA-G levels of the EOC patients in our study were significantly increased independent of the HLA-G 3′UTR haplotype implying that the tumor burden is the main source for the systemic release of sHLA-G molecules." (PMID 30932005, 2019).
tumor (continued). "Tumor cells have developed several mechanisms to evade from NK cell immunosurveillance, through the modulation of cell surface molecules involved in their recognition and the release of immunosuppressive soluble factors such as TGF-β, HLA-G, prostaglandins and adenosine in the TME." (PMID 30939820, 2019). "This may explain HLA-G expression in TAM and microglial cells in GBM tumor sections." (PMID 29467963, 2018). "In the current study, we investigated whether the proportion of immune effectors expressing ILT2 might be associated with recurrence in NMIBC, in relation or not with HLA-G expression at the tumor site." (PMID 30237859, 2018). "Furthermore, intercellular transfer of HLA-G from allogeneic as well as from autologous HLA-G positive tumor cells to HLA-G negative tumor cells via trogocytosis has been demonstrated." (PMID 30319626, 2018). "Thus, HLA-G is capable of inhibiting all actors of anti-tumor responses and in contrast to both CTLA-4 and PD-1, of blocking all stages of such an anti-tumor response, from the APC activation and effector priming, to the function of a fully activated cytotoxic T cell or NK cell." (PMID 30237859, 2018). "However, no data have been reported to date regarding the role of HLA-G variants in the modulation of CT-related toxicity in CRC and in other tumor settings." (PMID 28653974, 2017). "Nevertheless, HLA-G was still present at the surface of these cells exposed to hypoxic treatment, especially in JEG-3, suggesting that the protective effect against immune system attack could be maintained and favor tumor growth." (PMID 28781970, 2017). "They detected HLA-G overexpression in tumor samples from PC patients, but not in nontumor tissues." (PMID 27652273, 2016). "Thus, miR-548q, but not miR-628-5p is able to revert to the immune escape of HLA-G expressing tumor cells." (PMID 27057628, 2016). "Aberrant HLA-G expression has often been found in tumor lesions but is rare in adjacent “nontumor” tissue, and the expression of the nonclassical class Ib antigen in tumors has often been associated with tumor progression and a poor prognosis for cancer patients." (PMID 27999823, 2016). "In summary, novel findings in the last two years confirmed that the expression of HLA-G is generally detected in tumors but not in normal tissues, and such expression positively correlated with tumor progression, metastasis, invasiveness, and worse prognosis of patients." (PMID 27652273, 2016). "The autologous exchange of membrane-bound HLA-G1 between cells of the same tumor could not be investigated for lack of HLA-G expression at the surface of the tumors we obtained." (PMID 25887663, 2015). "Likewise, hypoxia is associated with increased HLA-G transcription in a series of HLA-G-negative tumor lineages, such as 1074mel and M8." (PMID 24741620, 2014). "As HLA-G is frequently expressed in high grade ovarian tumours and almost never in low grade tumours, the role of this molecule could be different within these tumour types." (PMID 24987709, 2014). "Thus, HLA-E may collaborate with HLA-G in the protection of TAM from NK cell lysis and in the establishment of a tolerogenic tumor microenvironment." (PMID 25202308, 2014). "Their results indicate that LIR-1 does only serve as a weak inhibitory NK cell receptor in the absence of HLA-G on tumor cells, but might be relevant in situations with low KIR expression as seen within the first months after stem cell transplantation (SCT)." (PMID 22844324, 2012). "Thus, aberrant HLA-G expression is found at a relatively high frequency in RCC and might participate in evasion of these tumor cells from immunosurveillance by inhibiting lysis of RCC cells by immune effector cells." (PMID 22640987, 2012). "However, it was previously reported that a broad spectrum of tumours often up-regulates the expression of non-classical HLA class I, like HLA-G which dampens the NK-cell responses by engaging inhibitory receptors ILT-2 and KIR2DL4." (PMID 19755991, 2009).